VHL (von Hippel-Lindau tumor suppressor)
Diseases named in the same sentence as VHL in open-access papers (continued):
Sharing a sentence is not in itself a finding about the gene and the disease.
tumor (continued). "Mutations of the von Hippel-Lindau (VHL) tumor-suppressor gene and the resultant overexpression of hypoxia-inducible factor (HIF)-1α protein are considered hallmarks of ccRCC." (PMID 30909494, 2019). "All sequences resulted wild type with the exception of a frameshift mutation in VHL gene [c.242 delC ins TG (p.Pro81Leu*50)] in one patient and retained in both tumor tissue and organoids." (PMID 30814510, 2019). "Using known information regarding SDHx and VHL mutation status of these tumor specimens, we calculated the average log2(fold-change) in gene expression for tumors of each of these molecular subtypes relative to other PPGL tumors." (PMID 31234811, 2019). "In humans, inactivation or mutation of the von Hippel-Lindau (VHL) gene results in tumor development in multiple tissues including the kidneys, pancreas, retina, uterus, central nervous system and the adrenal gland." (PMID 30413999, 2019). "The landmark discovery of the VHL tumor-suppressor gene and the observation that VHL is mutated in up to 90% of patients with ccRCC has helped elucidate the molecular interplay in the RCC tumor microenvironment." (PMID 31484560, 2019). "As a tumor suppressor, VHL, which is located on chromosome 3p25 and encodes 214 amino acids, is one of the most important genes associated with ccRCC." (PMID 31462894, 2019). "Altogether these results indicate an association of RSUME levels with VHL mutations and tumor progression." (PMID 30890701, 2019). "The situation is similar in RCC—a tumour that depends highly on VHL—where BAP1 loss was associated with an increased risk of RCC-related death, although the mechanism is also not yet understood." (PMID 31323773, 2019). "To investigate the role of BAP1 independently of chromosome 3 status, we analysed the association between BAP1 and HIF1a/VHL within the D3 and M3 tumours separately." (PMID 31323773, 2019). "These VHL-deficient human RCC xenografts initially respond to VEGFR TKI treatment with reduced tumor growth rates." (PMID 30796200, 2019). "We observed that the proteasomal inhibitor MLN 9708 dramatically repressed tumor growth in VHL-deficient RCC." (PMID 30902965, 2019). "von Hippel-Lindau (VHL) disease (MIM 193300) is a rare autosomal dominant cancer syndrome caused by germline mutations in the VHL tumor suppressor gene." (PMID 31068970, 2019). "Our MR discovery analysis of human PPGL tumors inferred EPAS1 perturbation in both SDH-loss and VHL-loss tumors, but the overall contribution to tumorigenic transcriptional patterns in both tumor types is underwhelming." (PMID 31234811, 2019). "Although the Sanger sequencing results revealed no variants in SNORD141A or SNORD141B, heterozygous variants in the VHL gene were confirmed in all four of the tumor tissues." (PMID 31317677, 2019). "It is well-documented that the mutation of the VHL tumor suppressor gene promotes the constitutive activation of HIF-1α and HIF-2α subunits in RCC." (PMID 30909494, 2019). "STF-62247 induces cytotoxicity and reduces tumor growth of VHL-deficient RCC cells through autophagy, as detected by western blotting analysis, flow cytometry, fluorescence microscopy, and electron microscopy." (PMID 29963226, 2018). "More recently, another study showed that depressed PBRM1 and VHL expression was associated with elevated tumor aggressiveness." (PMID 30349421, 2018). "At genetic level, 25 of 30 tumor samples (83.3%) were characterized by mutations in the VHL coding sequence." (PMID 29732003, 2018). "A second and related subtype comprised “BAP1 driven” cases characterized by tumor clones with BAP1 as a lone mutational driver in addition to VHL." (PMID 29656894, 2018).
tumor (continued). "The R200W mutation in VHL is associated with congenital polycythemia, while its tumor suppressor activities are considered to be close to wild type VHL." (PMID 30338240, 2018). "Still, we found concordance of genetic profiles identified in all 64 validated CCC and in 120 CRC-UMF, concerning both homozygous and heterozygous VHL mutations, as compared to corresponding tumor samples." (PMID 29732003, 2018). "A high percentage of ccRCCs has been shown to be associated with the inactivation of the von Hippel–Lindau (VHL) tumour suppressor gene." (PMID 29251173, 2018). "Although VHL-driven tumour models have been achieved, this was possible by mutating further tumour suppressor genes." (PMID 29450727, 2018). "Despite a significant mutation heterogeneity within ccRCC, VHL inactivation occurs ubiquitously across all tumor regions." (PMID 29562667, 2018). "Seven CCC and 16 CRC-UMF did not carry VHL mutations but were found in patients with wild-type VHL tumor tissue." (PMID 29732003, 2018). "This rare autosomal dominantly inherited disorder has an incidence of approximately 1 in 30,000 and is caused by constitutional mutations in the VHL tumour suppressor gene (TSG)." (PMID 29680948, 2018). "Von-Hippel Lindau (VHL) is an autosomal dominant hereditary cancer predisposition syndrome characterized by abberations in the VHL tumor supressor gene at chromosome location 3p25.3." (PMID 30340515, 2018). "We also found 21 CRC-UMF derived from 11 patients and exhibiting a distinct VHL mutational profile than that found in the corresponding tumor tissue, raising questions regarding their possible tumor or pre-tumor nature." (PMID 30177639, 2018). "An independent study has also confirmed this SLC7A5 elevation at RNA level in VHL-deficient ccRCC when compared with non-tumor samples." (PMID 29938199, 2018). "This leads to improved vascularization of the tumor and complements the effect of the VHL mutation, which results in subsequent increased expression of hypoxia inducible factors, both resulting in tumor growth." (PMID 30123419, 2018). "In these cases, not only the CCC but also all the CRC-UMF displaying the same VHL mutational profiles found in the tumor tissue are genetically proven to be tumor cells with pVHL LOF." (PMID 29732003, 2018). "29/30 patients harboured CRC (20 harboured CCC, 29 CRC-UMF) and 25/29 patients carried VHL mutations in their tumour." (PMID 29732003, 2018). "It is known that the wild-type allele of VHL is universally deleted in these cancers, as expected for a classic two-hit tumor suppressor gene." (PMID 29656891, 2018). "Promoter DNA methylation can cause transcriptional inactivation of certain tumour suppressors, including the VHL gene in renal cell carcinomas." (PMID 30006568, 2018). "In fact, envelop proteins from the human ERV E (HERV-E) can be re-expressed in VHL-deficient clear cell RCC tumor cells potentially triggering a T cell response and tumor rejection." (PMID 30534127, 2018). "Among those are extramedullary hematopoiesis or secretion of EPO by the tumor itself or its associated cysts as well as genetic mutations of the VHL gene." (PMID 30214643, 2018). "It was previously found that STF-62247 induces cytotoxicity and reduces tumor growth of VHL-deficient RCC cells via autophagy." (PMID 29963226, 2018). "What remains a significant challenge for providers is determining the optimal management strategy for VHL patients in which disease progression is attributed to manifestations of symptoms associated with new tumor development." (PMID 30042517, 2018). "This highly aggressive, chemotherapy resistant tumour type is characterised genetically by loss or mutation of von Hippel-Lindau (VHL) gene, proposed to occur in up to 80% of all ccRCC3." (PMID 29463811, 2018). "We also found that 21 CRC-UMF from 11 patients exhibited discordant VHL mutational profiles when compared to corresponding tumor samples." (PMID 29732003, 2018).
tumor (continued). "Twenty-one CRC-UMF derived from 11 of these patients were found to bear VHL mutations different from those of the primary tumor." (PMID 29732003, 2018). "VHL alteration was detected in 108 tumor samples: intragenic mutations in 98 patients (52%) and hypermethylation in 10 (5.3%)." (PMID 30149673, 2018). "Remarkably, all the remaining 57 CCC as well as 104 CRC-UMF exhibited identical VHL mutations as those detected in the corresponding tumor samples, indicating the neoplastic nature of cells classified as CRC-UMF by the cytopathologists." (PMID 30177639, 2018). "Several lines of evidence suggested that CARD9 linked the VHL tumor suppressor protein (pVHL) to trigger tumor-related signaling molecule, thereby controlling RCC cell growth." (PMID 29352133, 2018). "786‐O cells are derived from a ccRCC which, like most ccRCCs, harbors biallelic somatic mutations of the von Hippel‐Lindau (VHL) tumor suppressor gene." (PMID 29080283, 2018). "We consider that, since we found VHL mutations identical to those found in the tumor tissue in CRC having uncertain malignant features (CRC-UMF) and having acquired the capability to circulate in blood, those CRC with VHL mutation are in fact tumor cells." (PMID 30177639, 2018). "von Hippel-Lindau (VHL) disease is an autosomal dominantly inherited disorder caused by a germline mutation in the VHL tumor supressor gene." (PMID 29022557, 2018). "57/57 CCC and 104/125 CRC-UMF from the 25 patients with VHL-mutated tumor carried the same VHL mutation detected in the tumor." (PMID 29732003, 2018). "Tumor-specific genetic alterations (such as VHL loss) reveal not only the biological changes that drive tumor progression but also vulnerabilities that can be exploited therapeutically." (PMID 29562667, 2018). "Among them, 18 exhibited 57 CCC (along with 85 CRC-UMF) and 7 exhibited 19 CRC-UMF alone, which were found with the VHL mutational profile also identified in the corresponding tumor tissue." (PMID 29732003, 2018). "In our study on 15 paired tumor-normal ccRCC samples from Chinese patients, the mutation frequency of VHL was 66.67%, which was much higher than that in the WES study performed on 10 Chinese with ccRCC previously." (PMID 30349421, 2018). "On the other hand, it has been shown that HIF-2α regulates mTORC1 activity in VHL-deficient tumour cells through the transcriptional control of the amino acid transporter Slc7a5." (PMID 29671738, 2018). "In another group of 10 patients (33%) we found heterozygous VHL mutations in the tumor tissue and in the corresponding CRC." (PMID 29732003, 2018). "This study adds to the current understanding of the structure-function relationship of VHL mutations, which is important for risk stratification of future tumor development in the patients." (PMID 30105105, 2018). "We tested 30 patients with ccRCC, as this particular cancer is characterized by VHL mutations in up to 83% of cases, and included, as control samples, the corresponding tumorous tissues, and corresponding individual leukocytes." (PMID 29732003, 2018). "3p loss was subclonal in five tumors: one harboring a VHL mutation (K252), one VHL methylation (K070), one tumor that was VHL wild-type but SETD2 muttant (K427), and two with no mutations in any of the 3p genes (K169, K446)." (PMID 29656894, 2018). "HIF stabilization and activation of target genes is critical in the pathogenesis of ccRCC as HIF-2 has been shown to be both necessary and sufficient for tumor growth in VHL-deficient RCC cell lines." (PMID 29435132, 2018). "Somatic mutations that are found in all sampled tumour regions present in the trunk of the phylogenetic tree, including VHL mutations and 3p loss." (PMID 30099580, 2018). "In presence of VHL mutation the matrix fibronectin has decreased with presence of FN at varying levels in the cytoplasm of tumour cells." (PMID 30009029, 2018).
tumor (continued). "This combination of VHL loss often alongside areas of inadequate oxygen supply gives rise to a tumour environment that is characterised by high HIFα expression at a variety of oxygen tensions ranging from normoxia to severe hypoxia." (PMID 29463811, 2018). "Left K114 tumor harbored a VHL mutation and 3p loss, while in the right tumor we detected a clonal TCEB1 mutation with the loss of 8q21.11, encompassing the TCEB1 locus." (PMID 29656894, 2018). "It is widely acknowledged that loss or mutation of VHL occurs early in tumourigenesis, while hypoxic regions of tumours are associated with later disease stages when avascular or dysregulated angiogenesis, primarily mediated by VEGF, are commonplace." (PMID 29463811, 2018). "Mutation of the von Hippel–Lindau (VHL) tumour suppressor plays an essential role in the cellular oxygen-sensing pathway, which is correlated with poor prognosis in ccRCC patients." (PMID 29472550, 2018). "If a family history of VHL disease is present, a diagnosis of VHL disease can be made by finding only a single VHL-associated tumor." (PMID 29022557, 2018). "We also found 21 CRC-UMF derived from 11 patients which exhibited a distinct VHL mutation from that found in the corresponding tumor tissue, raising the issue of their possible pre-tumor nature and/or origin from a minority tumor cell clone." (PMID 29732003, 2018). "VHL-related HB arise from defects associated with loss of tumor suppression function of the VHL gene." (PMID 28868236, 2017). "Tumour‐initiating mutations in VHL lead to the activation of the transcription factor HIF2A, but this does not automatically lead to the acquisition of a metastatic phenotype." (PMID 27756687, 2017). "The VHL tumor suppressor is inactivated by mutation or epigenetic silencing in ~80% of sporadic clear cell RCC cases." (PMID 28247252, 2017). "We evaluated the subcellular localization of NOX4 by confocal microscopy in RCC cells deficient of the VHL tumor suppressor gene (786-O and A498) and normal renal epithelial (HK2) cells." (PMID 29051480, 2017). "When the VHL gene is mutated, its tumor suppressor function is lost and HIF accumulates to high levels, leading to the activation of multiple genes including vascular endothelial growth factor (VEGF) and platelet-derived growth factor (PDGF)." (PMID 28153029, 2017). "Germline inactivation of the von Hippel-Lindau (VHL) tumor suppressor predisposes patients to develop different highly vascularized cancers." (PMID 28425505, 2017). "VHL loss drives tumor angiogenesis and accounts for the clinical activity of VEGF receptor (VEGFR) tyrosine kinase inhibitors (TKIs), the first-line standard of care for advanced RCC." (PMID 28247252, 2017). "Clear-cell RCC (ccRCC), the most frequent and malignant type of RCC, is characterized by early loss of the von Hippel-Lindau (VHL) tumour-suppressor gene in most tumours." (PMID 28643803, 2017). "It is thought that loss of tumor suppressor function of the VHL gene results in stabilization of hypoxia-inducible factor alpha with downstream activation of cellular proliferative and angiogenic genes that promote tumorigenesis." (PMID 28868236, 2017). "Among the DEGs, Twist1 was found as an important gene closely linked to VHL silencing, which has been reported as an important regulator of tumor neovascularization." (PMID 28710479, 2017). "In this study, we show that telomere length is positively correlated with the onset age of five major VHL‐associated tumors in tumor‐affected mutation carriers." (PMID 28776935, 2017). "The overexpression of Dicer also has a suppressing influence on tumor growth and angiogenesis in VHL-deficient clear cell RCCs by reducing HIF2α expression, demonstrated in vivo and in vitro." (PMID 29165391, 2017). "Patients can have variable presentations; the diagnosis is often confirmed by positive family history and presence of one VHL-associated tumor." (PMID 28785532, 2017).
tumor (continued). "With an incidence of approximately one in 36,000 live births, VHL disease is an autosomal dominant multi-system neoplastic syndrome resulting from a germline mutation of the VHL tumor suppressor gene on the short arm of chromosome 3 (3p25-26)." (PMID 28948530, 2017). "Doxorubicin treatment significantly reduced tumour growth of VHL-deficient tumour cells compared with corresponding VHL-expressing tumour cells." (PMID 28643803, 2017). "Stabilisation of the HIF-1α subunit occurs, e.g., in the case of a deletion or inactivating mutation in the gene for the VHL protein, which determines the development of tumours, such as human glioblastoma or sporadic renal cell carcinoma." (PMID 27326424, 2017). "The expression of CK2α in high stage ccRCC (pT3-4) was compared with gender, age, Fuhrman grade, tumor size, Leibovich score, T-stage, metastasis and VHL mutation status." (PMID 27906674, 2017). "The inactivation or loss of the VHL tumour suppressor is the main molecular trigger for altered metabolism in ccRCC." (PMID 28165361, 2017). "The tumor suppressor effect of VHL protein disappeared when the two alleles of VHL gene were mutated or inactivated, leading to the occurrence of RCC." (PMID 28969028, 2017). "In this study, the authors demonstrate that VHL loss in these tumours augments anthracyclines chemotherapy by down-regulation of ALDH2." (PMID 28643803, 2017). "VHL is caused by a heterozygous germline mutation on the VHL tumour suppressor gene on chromosome 3p25.5 and contains three exons." (PMID 29166454, 2017). "In a multivariate cox regression analysis including the 40 patients with high stage ccRCC and the variables CK2α nuclear expression, Fuhrman grade G1-G2/G3-G4, tumor size <7/≥7 cm, VHL mutation and gender, nuclear expression of CK2α lost its prognostic value." (PMID 27906674, 2017). "All eight mutant samples showed a decrease of p21, Bax and Noxa RNA levels compared to VHL wild-type except for Noxa in the Cys162Arg mutated tumor." (PMID 28052007, 2017). "VHL-deficient tumor cell lines and patient-derived xenografts provide models for first-line therapy." (PMID 28247252, 2017). "M1 contains tumours with SDHx mutations and hypermethylation, M2 VHL-mutated tumours, and M3 tumours with NF1 and RET mutations and hypomethylation." (PMID 28327598, 2017). "In these tumors, activation of that pathway was associated to a pseudohypoxic tumor phenotype defined by the presence of VHL gene mutations, and accumulation of the CAIX protein." (PMID 28099149, 2017). "Libutti and colleagues recommended resecting VHL-associated PNETs if the tumor is greater than 3 cm and if the tumor is greater than 2 cm in the head of the pancreas to allow the chance of enucleation rather than resection of the head of the pancreas." (PMID 28948530, 2017). "VHL mutations were found to be universal throughout individual tumors when it occurred (ubiquitous), while the mutations in other tumor suppressor genes tended to be detected only in parts of the tumors (subclonal)." (PMID 27764136, 2016). "Regarding the age presentation, it has been proposed that patients with VHL have a heterozygous recessive tumor suppression gene mutation that requires a single mutation to develop a tumor." (PMID 27339157, 2016). "While the first-line treatment for both types of VHL-associated CNS tumors is surgery, the indications for treatment are patient specific and different for each tumor type." (PMID 27446927, 2016). "Depending on tumor type and location, current treatments for VHL-associated tumors can include a combination of chemotherapy, radiation therapy, and/or surgery." (PMID 27446927, 2016). "Patients with von Hippel–Lindau (VHL) disease harbor a germline mutation in the VHL gene leading to the development of several tumor types including clear cell renal cell carcinoma (ccRCC)." (PMID 27491085, 2016).